MEG3 (maternally expressed 3)
Diseases named in the same sentence as MEG3 in open-access papers (continued):
Sharing a sentence is not in itself a finding about the gene and the disease.
melanoma (continued). "In this report, the expression and function of MEG3, miR-499-5p, and CYLD were explored in melanoma tissues and cell lines." (PMID 29808164, 2018). "POU3F3 negatively influences MEG3 levels in melanoma cells, while overexpression of MEG3 does not affect POU3F3 levels, suggesting interactions between POU3F3 and other factors." (PMID 41463281, 2025). "In addition, another team showed that MEG3 modulated the expression of CYLD by targeting miR-499 and suppressed the proliferation and invasion of melanoma." (PMID 36544907, 2022). "Finally, the lncRNAs XIST, H19, MEG3, and LINC01291 were shown to confer resistance of melanoma cells to platinum compounds by regulating miR-21/PI3KR1 miR-18/IGF1, miR-499-5p/CYLD, and miR-625-5p/IGF-1R axis, respectively." (PMID 35159386, 2022). "In conclusion, POU3F3 is upregulated in melanoma and POU3F3 overexpression may promote melanoma cell proliferation by downregulating MEG3." (PMID 35201451, 2021). "In vitro experiments showed that POU3F3 overexpression decreased MEG3 expression in melanoma cells, while MEG3 overexpression failed to affect POU3F3." (PMID 35201451, 2021). "In the present study, POU3F3 overexpression downregulated MEG3 but failed to significantly affect the migration and invasion of melanoma cells." (PMID 35201451, 2021). "Hence, in this study, we selected 6 well-documented lncRNAs associated with metastasis including MALAT1, HOTAIR, NEAT-1, HULC, MEG-3, and UCA1 to evaluate their expression in primary melanoma and matched lymph node metastasis tissues." (PMID 23862139, 2013). "It was identified that the level of MEG3 and CYLD was significantly decreased, but the expression of miR-499-5p was dramatically increased in melanoma tissues and cell lines compared with paired nontumor tissues or HEMa-LP cells." (PMID 29808164, 2018).
liver cancer (27 papers, 2015 to 2025). An epithelial or non-epithelial malignant neoplasm that arises from the liver. "Nanoconjugates of the tumor suppressor MEG3 delivered intrahepatically to animals with liver cancer showed improvement in histopathology and tumor-associated biomarkers that was superior to that achieved with unconjugated MEG3." (PMID 37370745, 2023). "Intriguingly, knockdown of miR-493-5p is associated with the hypermethylation of the MEG3 differentially regulated region (DMR) in liver cancer." (PMID 35761379, 2022). "Since the loss of MEG3 has been reported in various types of human cancers, including gastric, prostate, hepatocellular, breast, and liver cancers, more previously research focused on MEG3 as a tumor suppressor in cell proliferation." (PMID 29238035, 2017). "To address whether MEG3 inhibits the growth of liver cancer stem cells and is associated with TERT or TRF2, we constructed related cell lines and then performed rescue experiments." (PMID 33256840, 2020). "Nano-conjugated MEG3 demonstrated a greater improvement in histopathology and tumor-associated biomarkers when administered intra-hepatically to liver cancer mice than unconjugated MEG3." (PMID 39912974, 2025). "MEG3 suppressed liver cancer cell growth by inhibiting β-catenin through the activation of PKM2 and inactivation of PTEN." (PMID 38827318, 2024). "The four lncRNAs HOTAIR1, MALAT1, MEG3 and H19 have been proved to be highly correlated with primary liver cancer." (PMID 34633988, 2021). "Our previous research found that long ncRNA MEG3 can form circular MEG3 (CircMEG3), and it is lowly expressed in human liver cancer." (PMID 33425489, 2021). "At the same time, MEG3 inhibits telomerase activity in human liver cancer stem cells by reducing the binding of TERT to TERC." (PMID 33256840, 2020). "In summary, our studies reveal that MEG3 significantly inhibits the growth of human liver cancer stem cells in vitro and in vivo." (PMID 33256840, 2020). "Our results demonstrate MEG3 inhibits the occurrence of human liver cancer and these, findings provide an important insight into the prevention and treatment of human liver cancer." (PMID 33256840, 2020). "In this study, we used isolated and identified human liver cancer stem cell hLCSCs to reveal that MEG3 can inhibit the growth of human liver cancer stem cells on epigenetic mechanisms." (PMID 33256840, 2020). "Collectively, these observations suggest that MEG3 inhibits the growth of human liver cancer stem cells." (PMID 33256840, 2020). "The decrease of telomerase activity and telomere stability is an important reason for MEG3 to inhibit the growth of human liver cancer stem cells." (PMID 33256840, 2020). "In this study, MEG3 inhibits human liver cancer stem cells and is involved in epigenetic regulation for histones and telomere lifespan." (PMID 33256840, 2020). "Collectively, these results suggest that excessive TERT or TRF2 abrogates the inhibitory effect of MEG3 on the growth of human liver cancer stem cells." (PMID 33256840, 2020).
liver cancer (continued). "In the same study, UHRF1 is identified as involved in the upstream regulation of MEG3 in liver cancer by regulating DNMT1." (PMID 31341758, 2019). "Next, we analyzed the expression of MEG3 and mature miR-493-3p/5p in liver cancer cells after demethylating treatment." (PMID 31320614, 2019). "In liver cancer tissues, MEG3 is negatively correlated with UHRF1 that plays an important role in DNA methylation by recruiting DNA methyltransferase DNMT1 during DNA replication." (PMID 31341758, 2019). "Other studies have shown that DNA methylation affects the expression of MEG3 and affects its targeting of miR-29 in liver cancer." (PMID 31584879, 2019). "Excessive MEG3 significantly decreased the growth of liver cancer cell Hep3B compared to the control cells (P < 0.01)." (PMID 29449541, 2018). "Our findings in this study provide a novel evidence for an active role of PKM2 in MEG3-mediated inhibition of liver cancer cell growth." (PMID 29449541, 2018). "Our observations demonstrated that MEG3 is crucial for the inhibition of cell growth and viability in liver cancer cells." (PMID 29449541, 2018). "Strikingly, we also demonstrated that MEG3 is closely associated with PTEN and β-catenin in liver cancer cells." (PMID 29449541, 2018). "Taken together, these findings demonstrate that MEG3 inhibits malignant progression of liver cancer cells in vitro and in vivo." (PMID 29449541, 2018). "Herein, our findings demonstrate that MEG3 inhibits the malignant progression of liver cancer cells in vitro and in vivo." (PMID 29449541, 2018). "Our findings demonstrate that MEG3 inhibits the malignant progression of liver cancer cells in vitro and in vivo." (PMID 29449541, 2018). "In the present study, we indicate that MEG3 inhibits the malignant progression of liver cancer cells in vitro and in vivo." (PMID 29449541, 2018). "On the other hand, the MEG3 expression were significantly decreased in liver cancer stem cell line compared to the liver cancer unstem cell line." (PMID 26513297, 2015). "MEG3 inhibited oncogenic C-Myc and β-catenin activity in liver cancer." (PMID 36851033, 2023). "Notably, aberrantly expressed miR-493-5p has been found correlated with hypermethylation of MEG3 in liver cancer cells and tissues." (PMID 35761379, 2022). "Among the four liver cancer cell lines, HepG2 and Huh7 expressed the lowest MEG3 abundance." (PMID 34895065, 2021). "Our findings indicate that MEG3 inhibits telomerase activity in human liver cancer stem cells." (PMID 33256840, 2020). "Our results demonstrates MEG3 inhibits the occurrence of human liver cancer by blocking telomere, and these findings provide an important insight into the prevention and treatment of human liver cancer." (PMID 33256840, 2020). "Furthermore, our results also indicate that MEG3 regulates the length of telomeres in human liver cancer stem cells." (PMID 33256840, 2020). "Notably, our results indicate that MEG3 inhibits the proliferation of human liver cancer stem cells in vitro and in vivo." (PMID 33256840, 2020). "It has been seen that MEG3 may inhibit the development of human liver cancer by altering several complex signaling pathways." (PMID 33256840, 2020). "Therefore, MEG3 inhibits the activity of telomerase and shortens the length of telomeres, thereby inhibiting the malignant progression of human liver cancer." (PMID 33256840, 2020). "Importantly, our findings demonstrated that both telomerase activity and telomere-stabilizing protein TRF2 were important reasons for MEG3 inhibiting human liver cancer stem cells." (PMID 33256840, 2020).
liver cancer (continued). "Notably, miR-493-5p epigenetic silencing was correlated with hypermethylation of the MEG3 differentially regulated region (DMR) in liver cancer cell lines and tumor tissues from patients." (PMID 31320614, 2019). "Significantly, we also found that excessive β-catenin abrogated the effect of MEG3 in liver cancer." (PMID 29449541, 2018). "To investigate whether MEG3 inhibited the malignant growth of human liver cancer cell line Hep3B, we first established two stable Hep3B cell lines transfectd with pCMV6-A-GFP (GFP ctrl), pCMV6-A-GFP-MEG3 (MEG3), respectively." (PMID 29449541, 2018). "β-catenin determines MEG3 suppressor function in liver cancer cells." (PMID 29449541, 2018). "MEG3 inhibits malignant progression of liver cancer cells in vitro and in vivo." (PMID 29449541, 2018). "Accordingly, reduction in PKM2 may partly contribute to MEG3-mediated inhibition of liver cancer cell growth." (PMID 29449541, 2018). "Our studies are now indicated to evaluate the effects of MEG3 in liver cancer cells." (PMID 29449541, 2018). "Taken together, β-catenin determines the MEG3 suppressor function in liver cancer cells." (PMID 29449541, 2018). "Furthermore, we also indicate that MEG3 enhances the TERRA expression by altering the epigenetic modification of the TERRA promoter region by affecting DNA methyltransferase activity in human liver cancer stem cells." (PMID 33256840, 2020). "Furthermore, we found that excessive β-catenin rescued the effect of MEG3 in liver cancer." (PMID 29449541, 2018). "Strikingly, our study also found that although MEG3 inhibited the growth of human liver cancer stem cells, the excess of telomerase reverse transcriptase TERT abolished the tumor suppressor function of MEG3." (PMID 33256840, 2020). "Collectively, these observations suggest that MEG3 inhibits β-catenin activity through PKM2 reduction and PTEN increase in liver cancer cells." (PMID 29449541, 2018). "Furthermore, MEG3 reduces the binding of TERC to TERT, thereby further inhibiting the activity of telomerase in human liver cancer stem cells." (PMID 33256840, 2020). "Our study suggests that MEG3 promotes the expression of TERRA and thus enhances the binding of TERRA to TERT, competitively inhibits the interaction of TERC with TERT, and ultimately inhibits telomerase activity in human liver cancer stem cells." (PMID 33256840, 2020). "Furthermore, MEG3 overexpression decreased the interaction between β-catenin and LEF, TCF4 in liver cancer cells." (PMID 29449541, 2018). "The present study depicts a novel evidence for MEG3 that plays inhibiting tumorigenesis roles by downregulating PKM2 and β-catenin in liver cancer cells, which may have potential therapeutic significance." (PMID 29449541, 2018). "To explore whether MEG3 influenced β-catenin activity, we analyzed the activity of β-catenin co-activators LEF and TCF-4 in liver cancer cells." (PMID 29449541, 2018). "MEG3 inhibits β-catenin activity through PKM2 reduction and PTEN increase in liver cancer cells." (PMID 29449541, 2018). "Moreover, we have clearly demonstrated that MEG3 inhibits METTL3 through blocking HULC in human liver cancer (data not shown)." (PMID 33425489, 2021). "Moreover, we have demonstrated that linear MEG3 inhibits METTL3 through blocking HULC in human liver cancer (data not shown)." (PMID 33425489, 2021).
liver cancer (continued). "Furthermore, MEG3 also inhibits CyclinD1 and C-Myc via PKM2 in liver cancer cells." (PMID 29449541, 2018). "Our study for the first time demonstrated that MEG3 acts as a tumor suppressor by negatively regulating the activity of the PKM2 and β-catenin pathway in hepatocarcinogenesis and may provide potential therapeutic targets for the treatment of liver cancer." (PMID 29449541, 2018). "However, MEG3 plus β-catenin did not significantly alter the PCNA positive rate of liver cancer cells (49.13 ± 12.38% versus 41.33 ± 7.88%, P = 0.237289 >0.05)." (PMID 29449541, 2018). "However, MEG3 plus β-catenin did not significantly alter the BrdU positive rate of liver cancer cells (56.43 ± 13.27% versus 52.4 ± 10.71%, P = 0.3793616 >0.05)." (PMID 29449541, 2018). "Furthermore, MEG3 inhibited CyclinD1 and C-Myc via PKM2 in liver cancer cells." (PMID 29449541, 2018). "However, MEG3 plus β-catenin did not significantly alter the colony formation rate of liver cancer cells (39.12 ± 10.6% versus 36.02 ± 7.26%, P = 0.1985 >0.05)." (PMID 29449541, 2018). "In conclusion, our study for the first time demonstrates that MEG3 acts as a tumor suppressor by negatively regulating the activity of the PKM2 and β-catenin signaling pathway in hepatocarcinogenesis and could provide potential therapeutic targets for the treatment of liver cancer." (PMID 29449541, 2018).
neuroblastoma (26 papers, 2005 to 2024). Neuroblastoma (NB) is the most common solid, extracranial childhood tumor. "Our previous studies demonstrated that MEG3 was significantly downregulated in neuroblastoma (NB) and its expression was negatively associated with the INSS stage." (PMID 33061817, 2020). "Low expression of MEG3 in patients had a higher NB risk, advanced International Neuroblastoma Staging System (INSS) stages, and faster disease progression." (PMID 33061817, 2020). "In summary, the present data indicate that MEG3 polymorphisms have low penetrant effects on neuroblastoma risk." (PMID 29615542, 2018). "Long noncoding RNA MEG3 polymorphisms have been shown to confer cancer susceptibility; however, their roles in the genetic predisposition to neuroblastoma remain unclarified." (PMID 29615542, 2018). "To answer this question, we genotyped two MEG3 polymorphisms, rs7158663 G>A and rs4081134 G>A, in 392 neuroblastoma children and 783 controls by TaqMan method." (PMID 29615542, 2018). "Herein, we are the first group to explore the association between MEG3 polymorphisms and neuroblastoma susceptibility in Chinese children." (PMID 29615542, 2018). "The results showed that neither single locus nor the combination analysis supported an association between MEG3 polymorphism and neuroblastoma risk." (PMID 29615542, 2018). "Null associations between MEG3 polymorphisms and neuroblastoma susceptibility were also observed for Guangdong and Henan subjects, individually." (PMID 29615542, 2018). "To determine the association of the MEG3 polymorphisms with neuroblastoma risk, we conducted this hospital-based case-control study in Chinese children." (PMID 29615542, 2018). "Our study provides evidence of the effects of MEG3 polymorphisms on neuroblastoma susceptibility." (PMID 29615542, 2018). "Therefore, we conducted a gene-based association analysis of MEG3 polymorphisms and neuroblastoma risk." (PMID 29615542, 2018). "Associations between MEG3 polymorphisms and neuroblastoma susceptibility." (PMID 29615542, 2018). "Stratification analysis of MEG3 polymorphisms with neuroblastoma susceptibility." (PMID 29615542, 2018). "Our data suggest MEG3 as a weak-effect neuroblastoma susceptibility gene." (PMID 29615542, 2018). "Moreover, in vitro and in vivo functional analysis is warranted to reveal the mechanism how the genetic polymorphisms in MEG3 affect the neuroblastoma risk." (PMID 29615542, 2018). "The lncRNA MEG3 is generally considered to be an important suppressor of neuroblastoma tumorigenesis." (PMID 38891878, 2024). "In this context, the lncRNAs MEG3, HCN3, and linc01105 have been identified as relevant in neuroblastoma tumorigenesis: their expression levels are associated with International Neuroblastoma Staging System (INSS) staging." (PMID 38891878, 2024). "MEG3 overexpression in neuroblastoma cell lines attenuated autophagy through inhibition of FOXO1 and EMT via the mTOR pathway." (PMID 38473229, 2024). "Nevertheless, MEG3 is often downregulated in neuroblastoma, resulting in elevated EZH2 levels; in this context, it is associated with poor INSS staging and survival." (PMID 38891878, 2024). "In contrast, in vitro MEG3 overexpression induced the repression of proliferation, cell cycle arrest, and stem cell properties and the promotion of apoptosis in several neuroblastoma cell lines." (PMID 38891878, 2024). "MEG3 has previously been shown to promote the aggregation of the mutant huntingtin gene in the neuroblastoma cell model of Huntington’s disease." (PMID 36552881, 2022). "This analysis revealed strong associations between the neuroblastoma lincRNAs MIAT and MEG3 and MYCN and PHOX2B activity or expression." (PMID 30952905, 2019). "However, the impacts of MEG3 polymorphisms in neuroblastoma risk remain unclear." (PMID 29615542, 2018).